CCAT2 (colon cancer associated transcript 2)
Diseases named in the same sentence as CCAT2 in open-access papers (continued):
Sharing a sentence is not in itself a finding about the gene and the disease.
cancer (continued). "A number of cancer-implicated lncRNAs, including FAL1, CCAT2, LINP1 (LncRNA In Non-homologous End Joining Pathway 1), and MALAT1, exert their functions through interaction with proteins." (PMID 32503290, 2020). "Thus, similar to ANRIL and CCAT2, PCAT1 is a major oncogenic lncRNA and potential prognostic and therapeutic cancer marker." (PMID 33329688, 2020). "However, transfection of CCAT2 using pMX retroviral nuclear expression vector only accumulated CCAT2 in the nucleus, leading to upregulation of OCT4-PG1, which positively regulated cancer cell stemness." (PMID 36672487, 2023). "In addition, CCAT2 expression was mainly upregulated in stage II tumor pathology, followed by stage III, indicating that CCAT2 could be used for the early detection of cancers." (PMID 34527584, 2021). "Whether the lncRNA CCAT2 expression level affects the clinical progression and outcome of cancer patients has not yet been fully elucidated." (PMID 32908615, 2020). "Moreover, CCAT2 might serve as a potentially molecular marker for LNM, DM, OS and MFS in human cancers." (PMID 29088900, 2017).
tumor (80 papers, 2013 to 2026). "LncRNA CCAT2 (Colon Cancer Associated Transcript 2) is located at the 8q24 region of the human genome and plays a role in tumor growth, metastasis, and destabilization of related chromosomal structures." (PMID 38334963, 2024). "Earlier studies found Colon cancer-associated transcript 2 gene (CCAT2) was high-expression in tumor and was associated with patient’s survival prognosis." (PMID 37598390, 2023). "The first indication of CCAT2 being a tumor-associated transcript came from the study of its encompassed SNP, rs6983267." (PMID 34830370, 2021). "Colon cancer associated transcript 2 (CCAT2) is a lncRNA that has been associated with tumor growth and chromosomal instability." (PMID 31772762, 2019). "Accumulating studies demonstrated that lncRNA colon cancer‐associated transcript 2 (CCAT2) acted as an oncogene in many tumours." (PMID 29502343, 2018). "This meta-analysis amied to explore the association between the expression level of CCAT2 and tumor metastasis & prognosis." (PMID 29088900, 2017). "Besides, overexpression of CCAT2 was significantly associated with tumor size, clinical stage, and TNM classification." (PMID 32908615, 2020). "We also detected the age-related effect of rs1867277 (FOXE1) conferring the higher risk for PTC in patients older than 55 years and the association of rs7267944 (DHX35) with PTC risk in males and that of rs6983267 (POU5F1B/CCAT2) with more advanced tumor pT stage." (PMID 33551988, 2020). "CCAT2 is associated with tumor grade and distant metastasis." (PMID 29416703, 2018). "However, the association of rs6983267 with tumor aggressiveness and its correlation with CCAT2 level are unclear." (PMID 29176650, 2017). "Taken together, these results supported the notion that CCAT2 up-regulation may be associated with tumor progression and development." (PMID 27283598, 2016). "In addition, we used our SNP data to associate CCAT2 transcript levels in 226 LNN patients with known DNA copy number to identify tumor samples with copy number alterations that showed concordant CCAT2 gene expression alterations." (PMID 24077681, 2013). "As a regulator of the WNT signaling system, CCAT2 increases cell proliferation in culture and tumor development in living organisms." (PMID 41459628, 2026). "Silencing CCAT2 stopped BC cells from multiplying, spreading, and going through the cell cycle in the lab and in living organisms, where it stopped tumor growth." (PMID 41459628, 2026). "CCAT2 inhibits the movement of pre-Mir-145 from the nucleus to the cytoplasm, thereby blocking the maturation of miR-145 and promoting tumor proliferation." (PMID 37020597, 2023). "CCAT2 (Colon-Cancer-Associated Transcript 2): CCAT2 is an exosomal long non-coding RNA primarily connected to CRC, and it facilitates tumor progression via PI3K/AKT/mTOR signaling." (PMID 37760852, 2023). "In summary, for the first time, the current study revealed a dual function of lncRNA CCAT2 as a tumor suppressor or oncogene depending upon its subcellular distribution." (PMID 36672487, 2023). "In conclusion, the current study, for the first time, revealed a dual function of lncRNA CCAT2 as a tumor suppressor or oncogene depending upon its subcellular distribution." (PMID 36672487, 2023). "After si‐CCAT2 or CCI‐779 treatment, the growth rate of transplanted tumours was inhibited, while promoted after CCAT2 overexpression." (PMID 35170195, 2022). "For example, such ECC DNA event led to the focal amplification of an oncogenic lncRNA CCAT2 in tumor ZLR-11." (PMID 35538075, 2022). "lncRNA CCAT2, whose role is well-known in tumours, has been studied in carotid plaque rupture and, interestingly, a positive correlation has been found between serum CCAT2 and plaque characteristics such as thickness." (PMID 35563540, 2022). "The results showed that the expression of miR-200b was reduced in ESCC tissues, while CCAT2 expression was elevated in the tumor samples." (PMID 34386421, 2021).
tumor (continued). "When comparing the tumor tissue with adjacent normal tissue in solid cancers, CCAT2 expression was upregulated in the tumor tissue, supporting its role as a potential biomarker." (PMID 34830370, 2021). "Expression of CCAT1, CCAT2 and c-Myc were significantly up-regulated in the tumours compared to matched mucosa (p < 0.0001)." (PMID 33432117, 2021). "As another ceRNA target of CCAT2, miR-143 is a tumor-suppressor miRNA with important roles in the inhibition of major oncogenes involved in proliferation and treatment resistance." (PMID 34830370, 2021). "The results indicated that CCAT2 expression levels in HCC tumour tissues were significantly higher than the corresponding adjacent tissues (p < 0.005)." (PMID 34409736, 2021). "lncRNA colon cancer-associated transcript 2 (CCAT2) expression is significantly increased in OSCC, and it is secreted into EXOs by tumour cells." (PMID 33478586, 2021). "On the other hand, MYC is one of the downstream targets of the Wnt/β-catenin pathway, highlighting the dual potentiating role of CCAT2 in this tumor-promoting feedback loop." (PMID 34830370, 2021). "We found decreased tumour growth rate and final smaller tumour size when CCAT2 was knocked down, while overexpressed CCAT2 promoted tumour growth (0.2839 ± 0.0321 cm3 vs. 0.1044 ± 0.0103 cm3, p < 0.001; 0.2568 ± 0.0178 cm3 vs. 0.6696 ± 0.1098 cm3, p < 0.01)." (PMID 34409736, 2021). "We measured the expression of CCAT1, CCAT2 and their oncotarget, c-Myc, in 150 matched mucosa-tumour samples of early-stage microsatellite-stable Chinese CRC patients with definitive metastasis status by multiplex real-time RT-PCR assay." (PMID 33432117, 2021). "Its expression was up-regulated even more than CCAT2 in the tumours compared to matched mucosa and account for a higher variability in c-Myc expression than CCAT2." (PMID 33432117, 2021). "SW620 cells infected with Ad-CCAT2, Ad-shCCAT2 or their controls were subcutaneously injected into the back of nude mice, and tumor volume and weight were measured." (PMID 34868956, 2021). "The effects of CCAT2 knockdown on in vivo tumor growth were determined using tumor xenografts and immunohistochemistry assays." (PMID 34499007, 2021). "For example, CCAT2 promotes its neoplastic regulatory functions through extensive ceRNA networks involving multiple tumor suppressor miRNAs, including miR-424, miR-145, miR-23b-5p, and miR-143." (PMID 34830370, 2021). "To further investigate the correlation between miR‐4496 (ELAVL1) and CCAT2 in HCC patients' tumour tissue, we examined miR‐4496 and ELAVL1 expressions by qRT‐PCR and IHC of 61 HCC specimens." (PMID 34409736, 2021). "In this study, we found the expression of CCAT1, CCAT2 and c-Myc to be significantly up-regulated in the patients’ tumours compared to matched mucosa." (PMID 33432117, 2021). "For example, colon cancer‐associated transcript 2 (CCAT2) and RNA associated with metastasis‐11 (RAMS11) have been reported to participate in the process of tumor invasion and migration." (PMID 34977870, 2021). "To identify the roles of CCAT2 as a potential tumour marker and provide the basis for prognosis prediction in HCC, we explored the functions and involved molecular mechanisms of CCAT2 in HCC metastasis in vitro and in vivo." (PMID 34409736, 2021). "CCAT2 is related to the stability of microsatellites; knockdown of CCAT2 inhibits tumor invasion and migration in mouse models." (PMID 34977870, 2021). "Box plot showed that the expression of CCAT1, CCAT2 and C-Myc in the tumours was significantly (up to hundreds-fold) up-regulated in the tumours compared to their matched mucosa (p < 0.0001)." (PMID 33432117, 2021). "Colon Cancer Associated Transcript 2 (CCAT2), another oncogenic lncRNA that controls tumor growth and dissemination by modulating Wnt and TGF-β signaling in BC, has been found in increased levels in tamoxifen-resistant BC." (PMID 32967267, 2020).
tumor (continued). "A study clarified that a high level of CCAT2 expression in CRC is associated with poor cell differentiation, deep tumor infiltration, increased lymph node metastasis, advanced TNM stage, and short DFS and OS." (PMID 31480503, 2019). "Silencing of CCAT2 (P < 0.01) significantly reduced PDAC tumor growth at 3 (P < 0.05) and 4 weeks (P < 0.05) after xenograft injections." (PMID 29298720, 2018). "Consistently, we found tumor size and weight were dramatically suppressed in the si-CCAT2 group, compared with those in the Scramble group." (PMID 29298720, 2018). "CCAT2 knock-down has resulted in the inhibition of cell proliferation and invasion in vitro and tumor formation in vivo." (PMID 28480695, 2017). "Further analyses were performed in patients with low CCAT2 transcript levels in tumor tissues, as compared with the corresponding ANCT, by dividing into two subgroups based on the relative transcript levels (>0.5 and <0.5)." (PMID 28480695, 2017). "The 48 patients were then divided into two groups by the median value of relative CCAT2 transcript levels in tumor tissues compared with the corresponding ANCT: high (n=12) and low (n=36) expression groups." (PMID 28480695, 2017). "CCAT2 (Colon cancer-associated transcript-2), a long noncoding RNA (lncRNA), has been reported to be over-expressed in CRC and is found to promote tumor growth." (PMID 28964256, 2017). "They found that genomic locus of CCAT2 is highly conserved and harbors the SNP rs6983267.It was highly expressed in microsatellite-stable colorectal cancer and promotes tumor growth, metastasis, and chromosomal instability." (PMID 29088900, 2017). "CCAT2 likely promotes chromosomal instability and tumor growth by activating WNT signaling and increasing MYC expression via activation of CDC25A, miR-17-5p, and miR-20a)." (PMID 27888635, 2017). "Down-regulation of CCAT2 expression had significantly reduced tumor growth compared with that of respective groups." (PMID 27833083, 2016). "Specifically, high expression levels of CCAT1 were associated with tumor growth, lymph node metastasis, and advanced TNM stage, whereas CCAT2 overexpression was related with increased metastatic and invasive potential of the tumor." (PMID 26064090, 2015). "This lncRNA, subsequently named colon cancer associated transcript 2 (CCAT2), was shown to have increased expression in metastatic CRC patient tumor samples." (PMID 25101115, 2014). "All the samples, both tumor and non-tumor tissues, showed a strong staining of CCAT2 in epithelial cells and a less intense staining in inflammatory and stromal cells." (PMID 24077681, 2013). "CCAT2 appeared to have higher expression in the epithelial component of BC tissue than in epithelial component of non-tumor tissue (P<0.001)." (PMID 24077681, 2013). "Apocrine metaplasia, columnar metaplasia and the usual intraductal epithelial hyperplasia disclosed a similar pattern of CCAT2 expression as the non-tumor breast tissue." (PMID 24077681, 2013). "Furthermore, pcDNA3.1-mediated overexpression of CCAT2 in MCF-7 cells significantly inhibited the tumor growth in vivo, decreased the levels of Ki67 and CCND1 and suppressed the expression of stemness genes." (PMID 36672487, 2023). "CCAT2 (colon cancer-associated transcription-2) is a long non-coding RNA (lncRNA) that positively regulates tumor growth, while miR-145 is a miRNA that negatively regulates gene expression." (PMID 37020597, 2023). "Transient transfection of CCAT2 increased the cytoplasmic localization of CCAT2, which sponged miR-221/222 through sequence complementarity, rescued the expression inhibition of p27 by miR-221/222, and thereby inhibited tumor growth." (PMID 36672487, 2023). "After removal of tumour in the nude mice, the mRNA level of CCAT2 was detected by RT‐qPCR." (PMID 35170195, 2022). "Upregulated lncRNA CCAT2 enhances tumor cell growth by controlling TGF-β1 signaling." (PMID 36482069, 2022).
tumor (continued). "The results showed that there was a significantly decreasing tendency in CCAT2 expression during D5–10 post-operation, which may be because the serum content of CCAT2 was decreased after resection of the tumor." (PMID 35115025, 2022). "Long non‐coding RNA (lncRNA) CCAT2 functions as an oncogene in a variety of tumours." (PMID 34409736, 2021). "Therefore, the tumor promoter effects of CCAT2 in ESCC are directed by the CCAT2/miR-200b sponging, which limits the miR-200b levels and inhibitory effect on IGF2BP2." (PMID 34830370, 2021). "CCAT2 significantly suppressed tumor growth and decreased the volume and weight of the tumors." (PMID 34499007, 2021). "Furthermore, HCC patients at stage III exhibited higher CCAT2 expression levels in tumour than those at stages I/II (0.00045 ± 0.00008 vs. 0.00022 ± 0.00005, p < 0.05)." (PMID 34409736, 2021). "In this study, we aimed to investigate whether the expression of CCAT1 and CCAT2 was coordinately upregulated in the same series of tumours and whether their up-regulation correlated with that of their target c-Myc in Singapore Chinese patients." (PMID 33432117, 2021). "In neuroblastoma, a malignant embryonal solid tumor that most frequently affects children, CCAT2 was found at increased levels in tumor tissue compared with adjacent normal tissue, and its expression was associated with increased cellular proliferation and lower three-year survival." (PMID 34830370, 2021). "CCAT2 overexpression in HCT116 cells leads to promotion of xenograft tumor formation in nude mice." (PMID 33246471, 2020). "Overexpression of CCAT2 in CRC cells could promote tumor growth, migration, and invasion in vitro and vivo and also induce chromosomal instability in vitro." (PMID 31480503, 2019). "CCAT2 facilitates proliferation and invasion of tumor cells, thus promoting PDAC progression." (PMID 29298720, 2018). "Recent studies have indicated that CCAT2 plays important roles in several tumours." (PMID 29502343, 2018). "However, in other patients, the level of CCAT2 transcripts was lower in tumor tissues compared with the corresponding ANCTs." (PMID 28480695, 2017). "However, further investigation is needed to explain the molecular mechanisms of CCAT2 in tumor development." (PMID 29088900, 2017). "These phenomena agree with previous reports that CCAT2 promotes tumor metastasis." (PMID 28964256, 2017). "In addition, multivariate analysis revealed CCAT2 expression level, distant metastasis, tumor grade, and FIGO stage to be independent prognostic indicators for overall survival (P < 0.05)." (PMID 27283598, 2016). "In addition, CCAT2 functions in tumor progression and invasion were further determined by siRNA-induced CCAT2 silencing in vitro." (PMID 27283598, 2016). "The overexpression of CCAT2 promotes tumor growth and metastasis in CRC mouse xenograft models." (PMID 26064090, 2015). "Although, after dividing the tumors at the median in groups containing a low (n=492, 30-68%) or high (n=505, >68%) percentage of invasive tumor cells, CCAT2 RNA levels were significantly higher in the group of tumors with high invasive tumor cells (Mann-Whitney U Test, P<0.001)." (PMID 24077681, 2013). "Colon cancer-associated transcript 1 (CCAT1) and colon cancer-associated transcript 2 (CCAT2), both located on chromosome 8q24.21, promote tumorigenesis by enhancing MYC expression and activating WNT/β-catenin signaling with elevated expression in tumor tissues." (PMID 41463069, 2025). "In addition, our assessment was based on the relative expression of CCAT2 in serum, and its expression in primary CC tumor tissues and cells remains to be further studies for the sake of providing more solid evidence for early diagnosis and prognostic prediction of CC." (PMID 35115025, 2022).